PTX3 (pentraxin 3)
Diseases named in the same sentence as PTX3 in open-access papers (continued):
Sharing a sentence is not in itself a finding about the gene and the disease.
colorectal cancer (13 papers, 2016 to 2025). A primary or metastatic malignant neoplasm that affects the colon or rectum. "Increased plasma levels of PTX3 are associated with a poor prognosis in colorectal carcinoma patients." (PMID 37063077, 2023). "Moreover, based on our observation that the positive association between PTX3 expression and stromal cells is linked to unfavorable survival outcomes in colorectal cancer patients, we proposed that PTX3 plays a role in stroma-mediated tumor progression." (PMID 38243273, 2024). "Furthermore, STAT3-mediated hypermethylation of enhancer 1 has been associated with PTX3 gene silencing in colorectal cancers." (PMID 31019517, 2019). "In one study on colorectal cancer, PTX3 emerged as a significant prognostic factor; in comparison, other markers, such as IL-6 and TNF-α, did not demonstrate the same prognostic utility." (PMID 39594709, 2024). "Depending on tumor stage, the PTX-3 gene is methylated differently through two enhancers: enhancer-1 is silenced in initial colorectal cancer stages, while enhancer-2 is stimulated during carcinoma progression." (PMID 36499628, 2022). "Researchers have also investigated in the past years the usefulness of PTX-3 as prognostic predictor in colorectal cancer." (PMID 36499628, 2022). "Epigenetic methylation of PTX-3 expression has been identified in colorectal cancer, revealing a possible onco-suppressor role of this acute phase protein." (PMID 36499628, 2022). "Studies on colorectal cancer reported evidence that methylation at the PTX3 promoter affects plasmatic PTX3 levels." (PMID 31969876, 2019). "It was shown furthermore, that in colorectal cancer cells, PTX3 is silenced by epigenetic modifications within these regions, that are, among other factors, induced by a high activity of STAT3 in these cells." (PMID 30774632, 2019). "In contrast, PTX3 expression is suppressed in other human tumors such as leiomyosarcoma and colorectal cancer." (PMID 27458153, 2016). "In colorectal cancer, pentraxin 3 is associated with poor prognosis but no mechanistic studies have clearly elucidated its effects." (PMID 36139106, 2022). "Recent studies have characterized these epigenetic mechanisms in the context of different PTX3 expressing cells, including macrophages and fibroblasts, and have further addressed the epigenetic modifications occurring in the PTX3 gene in colorectal cancer (CRC)." (PMID 31019517, 2019). "Similarly, in colorectal carcinoma (CRC), promoter methylation levels and CpG island methylation of the PTX3 gene increase hierarchically from normal epithelium to adenomas and to CRC, independent of cancer stage." (PMID 41479916, 2025). "Moreover, health professionals could assess patients with higher serum values of PTX-3 and could provide them with supplementary therapy or PTX-3 could also be considered a novel treatment target in case of colorectal cancer." (PMID 36499628, 2022).
fibrosis (13 papers, 2008 to 2025). the formation of excess fibrous connective tissue in an organ or tissue in a reparative or reactive process. "Decreased collagen accumulation, attenuation of alveolar fibrosis and fibrotic markers, and improved lung function were observed in bleomycin‐exposed conditional Ptx3‐deficient mice." (PMID 36336784, 2022). "In addition, a study of young Turkish adults showed that elevated plasma PTX3 levels were associated with the presence of fibrosis assessed based on liver biopsy in patients with NAFLD." (PMID 40066165, 2025). "Notwithstanding, the highest PTX-3 levels were noted in men with undetermined risk and women with a significant risk of fibrosis according to the HFSs; however, the difference was statistically significant only between undetermined and no advanced fibrosis subgroups." (PMID 40066165, 2025). "Therefore, we could not establish the sensitivity and specificity analysis for the diagnostic performance of PTX3 levels in assessment of fibrosis." (PMID 26997950, 2016). "In another study, it was found that plasma PTX-3 levels were significantly higher in NAFLD fibrosis stages 3–4 and correlated with them." (PMID 40066165, 2025). "In the evaluation of histoscores obtained from immunohistochemical staining for PODXL, PTX3, and ISM1, a statistically significant difference was observed between liver tissues with fibrosis associated with chronic hepatitis B and those from the control group." (PMID 41462970, 2025). "The study aimed to assess the relationship between plasma pentraxin 3 (PTX-3) levels and the potential diagnosis of fibrosis in metabolic dysfunction-associated steatohepatitis (MASH) in older adults." (PMID 40066165, 2025). "On this basis, in order to evaluate the modulation of PTX3 expression in the lungs during fibrosis onset, C57BL/6 male mice were treated intratracheal with BLM and sacrificed after 14, 21, and 28 days." (PMID 33679758, 2021). "Furthermore, compared to the low-grade fibrosis group, a statistically significant increase in PTX3 immunoreactivity was observed in the high-grade fibrosis group (p = 0.017)." (PMID 41462970, 2025). "The primary aim was to evaluate PTX3 to identify HCV patients who were in urgent need of antiviral treatments (METAVIR fibrosis F≥3) and those whose treatment could be deferred (METAVIR fibrosis F≥2)." (PMID 31061822, 2019). "In model 1, PTX3, ALT, and age were independently associated with presence of fibrosis in NAFLD after adjustment for age, smoking status, systolic and diastolic blood pressure, uric acid, AST, ALT, ALP, GGT, ferritin, and hs-CRP (P = 0.032, P = 0.002, and P = 0.01, resp)." (PMID 26997950, 2016). "In another study on patients with non-alcoholic fatty liver disease (NAFLD), those with NAFLD and fibrosis presented higher plasma levels of PTX3 than both NAFLD patients without fibrosis and the controls (p = 0.032 and p = 0.028, respectively)." (PMID 39519095, 2024). "In addition, the positive correlation between plasma PTX3 levels with NAFLD activity score, fibrosis stage, and steatosis grade has been described in adults." (PMID 32934654, 2020). "In the present study, we found that PTX3 levels were higher in NAFLD patients with fibrosis compared to NAFLD patients without fibrosis and control subjects." (PMID 26997950, 2016). "PTX3 levels in NAFLD patients with fibrosis were higher than both NAFLD patients without fibrosis and controls (P = 0.032 and P = 0.028, resp)." (PMID 26997950, 2016). "PTX3 levels were also less than 2 ng/mL in both NAFLD without fibrosis and control subjects." (PMID 26997950, 2016).
ischemic stroke (13 papers, 2013 to 2025). A stroke disorder caused by obstruction of blood flow to the brain, due to thrombotic (local blood clot formation) or embolic (due to a blood clot or other material traveling from another site) event. "This study aims to more thoroughly evaluate the association of plasma PTX3 levels and the incidence and severity of CAS in patients with ischemic stroke." (PMID 31998222, 2019). "In order to reflect the level of PTX3 more timely and accurately, we detected the concentration of PTX3 within 48 h after ischemic stroke." (PMID 31998222, 2019). "As observed in other tissues, PTX3 has been considered a new mediator of inflammation in cerebrovascular disorders and also be considered a potential prognostic marker in ischemic stroke." (PMID 31354697, 2019). "Our research group has previously demonstrated that PTX3 can promote neurogenesis after experimental ischaemic stroke." (PMID 30315331, 2018). "We propose that PTX3 can be targeted to promote long-term neurovascular repair and protect neurons after ischaemic stroke and possibly other cerebrovascular ischaemic injuries." (PMID 30315331, 2018). "A previous study has reported that an acidic microenvironment, similar to acidosis pH levels observed in ischaemic stroke, activates PTX3 into a tissue remodelling and repair mode in a lung injury model." (PMID 30315331, 2018). "In addition, serum levels of PTX3 are increased in patients affected by neurodegenerative disorders, including Parkinson’s disease, ischemic stroke, and multiple sclerosis." (PMID 36012705, 2022). "However, TIMP1 and PTX3 were also downregulated in astrocytes from Il1−/− mice but were both shown to play a protective role after ischemic stroke." (PMID 35384588, 2022). "If more patients were included and more investigations on vertebral artery and basilar artery were performed as well, we might have systemic assessment of the role of PTX3 in ischemic stroke." (PMID 31998222, 2019). "The close correlation observed between serum PTX3 levels and plaque vulnerability in the present study indicates that PTX3 may be a potential predictor of ischemic stroke." (PMID 24936646, 2014). "These included genes that have been previously associated with CVD in human studies such as PTX3 (pentraxin 3) and S100A12 (EN-RAGE), as well as genes that have been associated with CVD only in animal studies such as ANXA3 and SLPI, both shown to be up-regulated in rodent models of ischemic stroke." (PMID 32780732, 2020). "Here, we investigated for the first time the role of PTX3 in long-term CBF, angiogenesis, and neuronal viability after ischaemic stroke induced by transient middle cerebral artery occlusion (MCAo)." (PMID 30315331, 2018). "We therefore aimed to determine whether PTX3 KO mice have impaired recovery of CBF long-term (14 and 28 days) after ischaemic stroke." (PMID 30315331, 2018). "The severity of CAS was found to be correlated with PTX3 and TNF-α levels, which in turn might reflect the degree of inflammation, and may give predictive information about long term outcome in patients with ischemic stroke." (PMID 31998222, 2019).
lung disease (12 papers, 2011 to 2025). "Additionally, PTX3 has been implicated in the pathogenesis of various lung diseases through its involvement in numerous physiological and pathological processes." (PMID 40313930, 2025). "Invasive pulmonary disease (IPD) severity developed by patients and association with PTX3 haplotypes." (PMID 37222419, 2023). "PTX3 is a multifunctional acute phase protein that is elevated in cardiovascular, autoimmune, and pulmonary disease, and has been described as independent marker of inflammatory activity." (PMID 34064989, 2021). "However, various issues, including cellular responses to PTX3/CD44 interactions, their participation in pathogenic fibrogenesis in lung diseases and the details of PTX3/CD44‐involved molecular regulation in fibrosis, remain open questions." (PMID 36336784, 2022). "PTX3 has been reported to be upregulated and to play a protective role in various lung diseases." (PMID 33679758, 2021). "Finally, PTX3 has been proposed as a possible biomarker of disease in acute lung injury and other pulmonary disorders, including asthma, and lung carcinoma." (PMID 33679758, 2021). "Together, the long pentraxin PTX3 is required to suppress lung disease in systemic autoimmunity." (PMID 21637713, 2011). "We have identified significant differences in the association of plasma levels of long pentraxin-3, an innate immune mediator, and clara cell secretory protein, a marker of epithelial cell disruption, and PGD when comparing patients with fibrotic and non-fibrotic lung disease." (PMID 23284823, 2012).
osteoporosis (12 papers, 2017 to 2025). A condition of reduced bone mass, with decreased cortical thickness and a decrease in the number and size of the trabeculae of cancellous bone (but normal chemical composition), resulting in increased fracture incidence. "The ptx3 gene is significantly involved in the pathogenesis of age-related bone diseases, such as osteoporosis, in both mice and humans." (PMID 39857294, 2025). "This study investigates the role of circulating PTX3 as a marker of bone-related phenotypes in patients with osteoporosis (OP) and osteoarthritis (OA)." (PMID 33931080, 2021). "Regarding rheumatic diseases, PTX3 is involved in osteoblast proliferation in osteoporosis and its expression is induced by TNF-α in OA SF." (PMID 34208590, 2021). "Further characterization of this newly identified PTX3 for other potential ways and future study using animal models will shed light on its potential therapeutic implications for osteoporosis." (PMID 32436939, 2020). "The results showed that PTX3 expression was significantly lower in osteoporosis patients than in osteoarthritic and young subjects, which suggested that PTX3 plays a central role in osteoblast proliferation and differentiation." (PMID 32436939, 2020). "Noteworthy, in these studies the impairment of PTX3 expression was correlated to the occurrence of osteoporosis and more in general with a significant decrease of osteoblast differentiation." (PMID 33584725, 2020). "This experimental design will allow to both better elucidate the involvement of PTX3 in the bone mineralization process and demonstrate how PTX3 may represent a valid future therapeutic choice for the treatment of osteoporosis." (PMID 34073015, 2021). "Therefore, this study opens new and exciting perspectives about the possible role of PTX3 as biomarker and therapeutic agent for osteoporosis." (PMID 34073015, 2021). "Furthermore, given its involvement in bone metabolism, several studies agree with the definition of PTX3 as a molecule significantly involved in the pathogenesis of age-related bone diseases, such as osteoporosis, both in mice and humans." (PMID 33584725, 2020). "In addition, western blotting analysis showed reduced expression of NOX4 and increased expression of SIRT1 and PTX3 in both experimental groups, although with more pronounced effects in osteoarthritic patients, highlighting lower treatment efficacy in the presence of osteoporosis." (PMID 40956314, 2025). "Although serum PTX3 levels in patients with non-functional adrenal adenoma, acromegaly, renovascular hypertension and severe osteoporosis were under the first quartile, we could not observe certain trend in other diseases." (PMID 29715313, 2018).
preeclampsia (12 papers, 2013 to 2024). Preeclampsia is a hypertensive disorder of pregnancy that is characterized by new-onset hypertension with proteinuria presenting after 20 weeks of gestation, and depending on mild or severe forms may initially present with severe headache, visual disturbances, and hyperreflexia. "In addition, we included PTX3 as increased levels have been proposed to associate with preeclampsia." (PMID 34408755, 2021). "Circulating levels of PTX3 are high in preeclampsia, underlining the strong inflammatory response." (PMID 31057548, 2019). "However, increased levels of PTX3 have also been associated with preeclampsia." (PMID 34408755, 2021). "In addition, increased levels of PTX3 have been linked to preeclampsia." (PMID 34408755, 2021). "In addition, PTX3 levels in the first trimester were altered in women who subsequently developed preeclampsia, this confirming that an excessive inflammatory response is one of the causal factors causing preeclampsia in pregnant women." (PMID 31057548, 2019). "PTX3 has previously been investigated in placentas from pregnant women with late-onset preeclampsia and gestational diabetes mellitus." (PMID 38378837, 2024). "Earlier research on PTX-3 in NETs showed that PTX-3 plays a key role in regulating the proper development of pregnancy and the inflammatory response, such as in preeclampsia." (PMID 32753622, 2020). "Although not the focus of our study, we also observed markedly enhanced PTX3 levels in preeclamptic women at all time points, supporting a number of publications showing that PTX3 is closely correlated with the severity and progression of preeclampsia." (PMID 26842615, 2016). "Indeed, PTX3 levels are markedly elevated in women with preeclampsia and type 1 diabetes during pregnancy, and have been shown to correlate with the degree of glucose intolerance in women with GDM." (PMID 26842615, 2016). "For instance, elevated plasma levels of PTX3 associate to VCAM-1, flow-mediated dilatation and cardiovascular outcomes in CKD patients, as well as with altered endothelial function during preeclampsia." (PMID 23658833, 2013). "Raised CRP and PTX3 levels may indicate infection and preeclampsia, respectively." (PMID 34408755, 2021). "This may reflect a feedback mechanism aimed at counterbalancing overactive pro-inflammatory signals, and some studies have suggested that the increased levels of PTX3 observed in preeclampsia may have a placental origin coming from the increased number of macrophages in the placental bed." (PMID 26842615, 2016). "It has been demonstrated that the expression of PTX3 in the peripheral blood is closely related to preeclampsia, but no such pregnancy complications has yet been firmly established for CRP." (PMID 34408755, 2021). "It is clear that the regulation of PTX3 in pregnancy is complex, and the different profiles observed in GDM and preeclampsia patients may reflect contributions from different sources depending on the presence and extent of acute or chronic inflammatory conditions." (PMID 26842615, 2016).
viral infections (12 papers, 2011 to 2025). "The mechanisms behind the functions of PTX3 in association with NETs are unclear, as the roles of PTX3 in the neutrophilic response to viral infections." (PMID 34357089, 2021). "Collectively, our study identified a previously undescribed pathogenic role of PTX3 during virus infection and shed insights into the sophisticated innate immune responses launched against virus invasion." (PMID 25695775, 2015). "PTX3 is also considered a limiting factor in the development of bacterial, fungal, and viral infections and a prognostic indicator in the course of infection; its concentration is inversely proportional to the severity of infection." (PMID 39124846, 2024). "Second, we showed acute MIS-C patients had high plasma levels of pentraxin-3 (PTX3), an important innate immune mediator of resistance to viral infection and regulator of inflammation." (PMID 34632327, 2021). "Our findings demonstrate a previously undescribed pivotal role of PTX3 in shaping alphaviral disease progression through immunomodulation and facilitating viral infection and replication processes during the acute phase of infection." (PMID 25695775, 2015). "Following viral infection, PTX3 concentrations increase quickly and correlate closely with disease severity, suggesting it as a potential biomarker for the diagnosis and prognosis of viral infections in the lungs." (PMID 40313930, 2025). "PTX3 is a crucial mediator of inflammation and immunity, and it is especially increased in response to initial pro-inflammatory signals linked to TLR activation, pathogens, and viral infections as well as following tissue injury." (PMID 37762499, 2023). "Overexpression of PTX3 has protective effector function during bacterial infection with Aspergillus fumigatus, Pseudomonas aeruginosa and uropathogenic Escherichia coli, as well as viral infections such as murine cytomegalovirus and influenza virus." (PMID 25695775, 2015). "Further research should also assess PTX3 levels in different settings, i.e. in patients with SIRS, in trauma patients and in viral infections." (PMID 21423699, 2011). "Our results support the hypothesis that PTX3 can be used as a biomarker to discriminate bacterial meningitis from viral infections and is a promising clinical decision tool to rule out bacterial meningitis." (PMID 36862691, 2023). "The compelling evidence that PTX3 is an effective mediator in preventing CMV infection and reactivation as well as subsequent superinfections pinpoints a potential role for PTX3 as a biomarker and therapeutic agent in viral infections and superinfections in the transplantation setting." (PMID 30766534, 2019).